MRPS28 (mitochondrial ribosomal protein S28)
Synonyms: MRP-S28; MRP-S35; MRPS35; HSPC007; COXPD47
Tractability: Small molecule: a structure with a bound ligand is known. PROTAC: ubiquitination databases record sites on it; its protein half-life has been measured.
Target class: Other cytosolic protein
Gene: Protein-coding gene on chromosome 8 (79,918,401 to 80,030,304, reverse strand). Ensembl gene ENSG00000147586.
Subcellular location: Mitochondrion
Subcellular location (Human Protein Atlas): Mitochondria
Pathways (Reactome):
Metabolism of proteins: Mitochondrial ribosome-associated quality control; Mitochondrial translation elongation; Mitochondrial translation initiation; Mitochondrial translation termination
Gene Ontology:
Molecular function: RNA binding
Biological process: mitochondrial translation
Cellular component: mitochondrion; mitochondrial inner membrane; mitochondrial small ribosomal subunit
Genetic constraint (gnomAD): Loss-of-function variants: 14 observed, 13.15 expected, observed/expected ratio (o/e) 1.06, 90% interval 0.7 to 1.64. The upper end of that interval is the gene's LOEUF score, 1.64, which puts it in group 6 of 6, group 1 being the genes least tolerant of losing a copy. Missense variants: 260 observed, 239.37 expected, observed/expected ratio (o/e) 1.09, 90% interval 0.98 to 1.2. Synonymous variants: 121 observed, 96.86 expected, observed/expected ratio (o/e) 1.25, 90% interval 1.08 to 1.45.
Gene-disease validity (ClinGen):
ClinGen rates the evidence that MRPS28 causes each of these diseases.
mitochondrial disease (autosomal recessive): Limited.
Homologues: Orthologues: macaque MRPS28 (93% identical), pig MRPS28 (85% identical), dog MRPS28 (78% identical), mouse Mrps28 (73% identical), rabbit MRPS28 (53% identical), tropical clawed frog mrps28 (51% identical), zebrafish mrps28 (50% identical), rat Mrps28 (39% identical), Drosophila melanogaster mRpS28 (37% identical), Caenorhabditis elegans mrps-28 (31% identical).
Diseases named in the same sentence as MRPS28 in open-access papers:
MRPS28 is named in the same sentence as 6 diseases in open-access papers, as found by Europe PMC text mining. Sharing a sentence is not in itself a finding about the gene and the disease. The quoted sentences say what the papers report.
breast carcinoma (3 papers, 2022 to 2026). "However, ERAL1 is involved in the formation of the 28S small mitochondrial ribosomal protein (MRPS28) and that protein has been shown to be involved with breast cancer proliferation and metastasis." (PMID 35902644, 2022). "In addition, the biological function of MRPS28 in breast cancer was investigated." (PMID 41853286, 2026). "Mitochondrial Ribosomal Protein S28 (MRPS28) is a member of a family of proteins which are involved with mitochondrial energy metabolism which have been implicated in breast cancer prognosis and members of the MRP family have been shown to differentially expressed based on breast cancer subtype." (PMID 37621676, 2023).
glioblastoma (2 papers, 2021). The most malignant astrocytic tumor (WHO grade IV). "Likewise, the inhibition of MRPS28 is related to the treatment of glioblastoma with Benzyl isothiocyanate (BITC)." (PMID 34899304, 2021). "Furthermore, some evidence suggests that several genes expressing MRPs including bS1m (MRPS28), uS2m (MRPS2), uL23m (MRPL23), uS12m (MRPS12), bL12m (MRPL12) and mS34 (MRPS34) may be potential biomarkers for the treatment of glioblastoma with Benzyl isothiocyanate (BITC)." (PMID 34071057, 2021).
bladder cancer (1 paper, 2021). "A study also implicated MRPS28 in the molecular pathogenesis of bladder cancer." (PMID 34760386, 2021).
malignant lymphoma (1 paper, 2021). "RPS21, MRPS28, RPL31, and RPL30 showed relatively higher protein expressions in some DLBCL and other malignant lymphoma tissues than the averaged expressions in normal tissues, though not significant." (PMID 34760386, 2021).
cancer (1 paper, 2026). A tumor composed of atypical neoplastic, often pleomorphic cells that invade other tissues. "However, the effect of MRPS28 in pan-cancer remains unknown." (PMID 41853286, 2026).
MRPS28 also shares sentences with these, for which no sentence is quoted: diabetes (1 paper).